EGFR (epidermal growth factor receptor)
Diseases named in the same sentence as EGFR in open-access papers (continued):
Sharing a sentence is not in itself a finding about the gene and the disease.
metastatic colorectal cancer (continued). "Erlotinib (TarcevaTM, OSI-774), a potent epidermal growth factor receptor tyrosine kinase inhibitor (EGFR), was evaluated in a phase II study to assess its activity in patients with metastatic colorectal cancer." (PMID 16570047, 2006). "In summary, resistance to anti-EGFR therapy, whether intrinsic or acquired, remains a major obstacle in the treatment of metastatic colorectal cancer." (PMID 40940901, 2025). "For example, Cetuximab and Panitumumab were originally approved (in 2004 and 2006 respectively) to target the epidermal growth factor receptor (EGFR) which may be overexpressed in patients with metastatic colorectal cancer (mCRC)." (PMID 40175893, 2025). "In this multicenter, retrospective study utilizing real-world data from Turkey, we evaluated the efficacy and safety of adding anti-EGFR or anti-VEGF therapy to fluorouracil-based treatment in patients with isolated liver metastatic colorectal cancer (mCRC) who underwent conversion surgery." (PMID 40428735, 2025). "This study suggests that a facial skin type with a high number of enlarged pores may be a marker for predicting AfR risk due to anti‐EGFR antibody therapy and better therapeutic effects for RAS wild‐type metastatic colorectal cancer." (PMID 40503645, 2025). "This implies that the interaction between immune regulation and EGFR signaling may influence how the KIR–HLA profile predicts treatment outcomes in KRAS-WT metastatic colorectal cancer patients." (PMID 40869384, 2025). "RNF43, a WNT signaling pathway negative regulator, can predict the response of BRAF V600E MSS metastatic colorectal cancer against BRAF/EGFR combination therapy, where MSI-H always carries RNF43 wildtype-like, encoding p.G659fs* and presents an intermediate response frequency." (PMID 40860811, 2025). "Panitumumab is a human anti-epidermal growth factor receptor (EGFR) monoclonal antibody indicated in the treatment of patients with wild type Ras (WT) metastatic colorectal cancer (mCRC), Panitumumab works by binding to the extracellular domain of the EGFR preventing its activation." (PMID 39945465, 2025). "Background/Objectives: Metastatic colorectal cancer (mCRC) is mainly treated with 5-Fluoro-Uracil (5-FU), Oxaliplatin and Irinotecan chemotherapies and anti-Epidermal Growth Factor Receptor (EGFR) or anti-Vascular Endothelial Growth Factor (VEGF) targeted therapies." (PMID 39796718, 2024). "Subsequently, anti-EGFR monoclonal antibodies (mAbs) were developed, particularly cetuximab and panitumumab, and these have changed the treatment landscape for many patients with metastatic colorectal cancer (mCRC)." (PMID 38402342, 2024). "Another Phase II study suggested that the combination of erlotinib with irinotecan and the anti-EGFR antibody panitumumab might offer improved efficacy and a good safety profile in metastatic colorectal cancer patients, meriting further investigation." (PMID 39033209, 2024). "Indeed, mutations in RAS were strongly associated with worse overall survival and these genetic alterations are a predictive biomarker of resistance to anti-EGFR therapy in metastatic colorectal cancer (mCRC)." (PMID 39329997, 2024). "The objective of this translational research was to evaluate the potential of genome-wide DNA methylation status as a predictive biomarker for the effectiveness of anti-EGFR antibodies in the second-line treatment for patients with metastatic colorectal cancer." (PMID 38862615, 2024). "Corresponding clinical trials have been conducted in a population of chemotherapy-refractory metastatic colorectal cancer patients, demonstrating that the combination of cetuximab (anti-EGFR monoclonal antibody) and KRASG12C inhibitor adagrasib is more effective than adagrasib monotherapy." (PMID 39113889, 2024).
metastatic colorectal cancer (continued). "Primary tumor (PT) sidedness is an established prognostic marker in metastatic colorectal cancer (mCRC) and has a predictive impact on the efficacy of anti-epidermal growth factor receptor (anti-EGFR) antibody [monoclonal antibody (mAb)] in patients with RAS wild-type mCRC." (PMID 39173562, 2024). "Consequently, the interest in incorporating EGFR inhibitors like erlotinib into irinotecan-based regimens is increased in metastatic colorectal cancer and potentially increasing in other cancers." (PMID 39033209, 2024). "In the following year, phase III clinical trials brought great encouragement to the anti-EGFR therapy by suggesting that FOLFIRI plus cetuximab might be preferred for patients with metastatic colorectal cancer that is KRAS exon 2 wild-type." (PMID 38706597, 2024). "Similarly, in 2006, Vectibix (panitumumab), the first fully human antibody generated from transgenic mice, was approved for the treatment of metastatic colorectal cancer by targeting the Epidermal Growth Factor Receptor (EGFR)." (PMID 39584990, 2024). "Epidermal growth factor receptor (EGFR)-targeted therapy is an important treatment for RAS wild-type metastatic colorectal cancer (mCRC), but the resistance mechanism remains unclear." (PMID 38715141, 2024). "Similarly, cetuximab, which targets EGFR, has been authorized for treating metastatic colorectal cancer and head and neck cancer, among others." (PMID 38713378, 2024). "derived implications from previous clinical trials and cohort studies that KRAS mutations may have a stronger effect on prognosis in patients with metastatic colorectal cancer, and discussed possible biomarkers to recognize resistance to EGFR inhibition." (PMID 38706597, 2024). "Recently, in the phase III trial CodeBreaK 300 investigating KRAS G12C inhibitor plus an EGFR inhibitor in patients with chemorefractory metastatic colorectal cancer, both doses of sotorasib in combination with panitumumab resulted in longer progression-free survival than standard treatment." (PMID 39199633, 2024). "In the context of systemic chemotherapy for metastatic colorectal cancer (mCRC), new molecular targeted agents such as anti-vascular endothelial growth factor antibodies, anti-epidermal growth factor receptor (EGFR) antibodies, and multi-tyrosine kinase inhibitors were sequentially introduced." (PMID 38862615, 2024). "The available evidence regarding anti–epidermal growth factor receptor (EGFR) inhibitor rechallenge in patients with refractory circulating tumor DNA (ctDNA) RAS/BRAF wild-type (wt) metastatic colorectal cancer (mCRC) is derived from small retrospective and prospective studies." (PMID 38592721, 2024). "Adding anti-epidermal growth factor receptor (anti-EGFR) target agents to conversion therapy may improve the resection rates and survival of patients with potentially resectable metastatic colorectal cancer (mCRC)." (PMID 37880688, 2023). "Does an anti–epidermal growth factor receptor rechallenge approach for RAS wild-type metastatic colorectal cancer (MCRC) using panitumumab plus trifluridine-tipiracil lead to improved progression-free survival (PFS) compared with the standard-of-care trifluridine-tipiracil?" (PMID 37200022, 2023). "Anti-BRAF/EGFR therapy is approved for metastatic colorectal cancer (mCRC) with BRAFV600E mutations, although not all patients respond." (PMID 36779536, 2023). "Several clinical trials have explored the use of cetuximab or panitumumab monoclonal antibodies (mAbs) to target the Epidermal Growth Factor Receptor (EGFR) in the treatment of RAS wild type (WT) metastatic colorectal cancer (mCRC) among different lines of treatment." (PMID 36860319, 2023).
metastatic colorectal cancer (continued). "Anti-EGFR therapies, specifically anti-EGFR monoclonal antibodies such as cetuximab and panitumumab, combined with chemotherapy have resulted in a survival benefit for patients with left-sided metastatic colorectal cancer (mCRC) with RAS/RAF wildtype tumors." (PMID 37791069, 2023). "Targeting EGFR signaling through EGFR inhibitors profoundly impairs the tumor progression; however, monoclonal antibodies blocking the ligand binding to EGFR, have shown modest activity as a single agent in patients with metastatic colorectal cancer in clinical trials." (PMID 37853459, 2023). "Studies show that therapies targeting the VEGF and EGFr may be effective if introduced in later lines of therapy in the palliative setting of metastatic colorectal cancer." (PMID 37296984, 2023). "All patients with suspected or confirmed metastatic colorectal cancer should be genotyped for tumor tissue RAS mutations, as these mutations predict resistance to the anti-epidermal growth factor receptor (EGFR) monoclonal antibodies, cetuximab and panitumumab." (PMID 37760468, 2023). "The rechallenge strategy is based on the concept that a subset of patients with RAS wild‐type (WT) metastatic colorectal cancer (mCRC) could still benefit of epidermal growth factor receptor (EGFR) inhibition, after progression to an anti‐EGFR based‐therapy." (PMID 36880426, 2023). "Two drugs in CRC treatment are approved, and they include Bevacizumab, which targets a cancer cell protein called the vascular endothelial growth factor (VEGF), and Cetuximab, which is an epidermal growth factor receptor (EGFR) inhibitor drug used for the treatment of metastatic colorectal cancer." (PMID 35745786, 2022). "For example, not treating a patient with a KRAS mutated metastatic colorectal cancer with an EGFR inhibitor saves many thousands of dollars of drug cost using a test that costs hundreds of dollars." (PMID 36077668, 2022). "Studies evaluating circulating tumor DNA as a screening tool to detect patients who could benefit from EGFR antibody re-challenge in metastatic colorectal cancer." (PMID 36248993, 2022). "Among treatment options for metastatic colorectal cancer (mCRC), cetuximab and panitumumab are two distinct monoclonal antibodies (mAbs) targeting the EGFR, currently indicated for the same subgroup of patients, those with RAS wild-type (wt) metastatic disease." (PMID 35578244, 2022). "The KRAS mutation test is one of the main tests to determine whether the EGFR pathway is functioning properly when anti-EGFR agents are prescribed in patients with metastatic colorectal cancer." (PMID 36083889, 2022). "Combinations of cytotoxic agents including fluoropyrimidine (FP), oxaliplatin and/or irinotecan in combination with either anti-VEGF or, for RAS WT tumors, anti-EGFR antibodies represent the current standard of first-line treatment for patients with metastatic colorectal cancer (mCRC)." (PMID 35897060, 2022). "However, only 10% of patients with metastatic colorectal cancer showed clinical responses after monotherapy with anti-EGFR mAbs." (PMID 35035479, 2022). "Panitumumab is a monoclonal antibody against the epidermal growth factor receptor used in metastatic colorectal cancer; in addition to tumor cells, it acts on epidermal keratinocytes and on the outer root sheath and presents skin toxicity in up to 90% of cases." (PMID 35042642, 2022). "Thus, two EGFR‐directed mAbs (cetuximab and panitumumab) were approved by the FDA for EGFR-positive metastatic colorectal cancer." (PMID 36209184, 2022). "KRAS mutations, present in over 40% of metastatic colorectal cancer (mCRC), are negative predictive factors for anti-EGFR therapy." (PMID 35251991, 2022). "Furthermore, the anti-epidermal growth factor receptor (EGFR) mAb cetuximab, used for treatment of metastatic colorectal cancer, improves the overall survival of patients with wild-type K-ras tumors." (PMID 36015242, 2022).
metastatic colorectal cancer (continued). "Targeted therapies against vascular endothelial growth factors (VEGF) e.g. bevacizumab, and epidermal growth factor receptors (EGFR) e.g. cetuximab or panitumumab, are also recommended for first line management of patients with metastatic colorectal cancer in combination with cytotoxic chemotherapy." (PMID 33794823, 2021). "Because of the over-expression of EGFR in many epithelial solid tumors, EGFR-functionalized gold nanoparticles labeled by 89Zr displayed high tumor contrast in a metastatic colorectal cancer model as a result of selective accumulation and retention of these nanoparticles in the tumor tissue." (PMID 33718979, 2021). "It is clear that Epidermal Growth Factor Receptor (EGFR) inhibitors could provide a beneficial clinical outcome for metastatic Colorectal Cancer (mCRC) patients with wild-type rat sarcoma viral oncogene homolog (RAS) genes rather than mutant types." (PMID 34395262, 2021). "The epidermal growth factor receptor (EGFR)-targeted antibodies cetuximab and panitumumab can treat metastatic colorectal cancer (mCRC) negative for mutations in KRAS and NRAS exons 2–4." (PMID 34840814, 2021). "The addition of epidermal growth factor receptor (EGFR) targeting monoclonal antibodies (mABs) cetuximab and panitumumab to treatment protocols has improved survival rates in patients with metastatic colorectal cancer (CRC) as has been shown in numerous clinical trials." (PMID 34271981, 2021). "Anti-EGFR antibodies have activity as monotherapy or in combination with chemotherapy in RAS wildtype metastatic colorectal cancer; however their role in first-line treatment in combination with 5-fluorouracil monotherapy or when given alone has not been well studied." (PMID 34407800, 2021). "CALGB/SWOG 80405, Fire-3 and PEAK randomised controlled trials have all firmly established bevacizumab (VEGFR-inhibitor), cetuximab and panitumumab, (EGFR inhibitors) as first-line therapies in addition to FOLFOX/FOLFOXIRI in the management of patients with metastatic colorectal cancer." (PMID 34298779, 2021). "We aimed to assess the safety and efficacy of combination treatment with panitumumab plus trifluridine/tipiracil (FTD/TPI) in patients with wild-type RAS metastatic colorectal cancer (mCRC) who were refractory/intolerant to standard therapies other than anti-epidermal growth factor receptor therapy." (PMID 33928486, 2021). "EGFR is one of the most promising targets for the management of metastatic colorectal cancer." (PMID 33758598, 2021). "Alterations in the transcriptional factor c-MYC could be involved in the anti-EGFR resistance in metastatic colorectal cancer (mCRC)." (PMID 32164324, 2020). "Moreover, cetuximab and panitumumab, as monoclonal antibodies directed against EGFR, confer little benefit to patients with metastatic colorectal cancer if the primary tumor originated on the right side 16-18." (PMID 33033504, 2020). "Patients with metastatic colorectal cancer (mCRC) may be treated with targeted therapies directed against epidermal growth factor receptor (EGFR)." (PMID 32415199, 2020). "A prospective phase II clinical trial (PROSPECT-C) of single agent anti-EGFR therapy in patients with RAS WT metastatic colorectal cancer (mCRC) found that almost half of patients harbored pre-existing alterations in the RAS pathway, detectable at baseline cfDNA evaluation." (PMID 33383664, 2020). "Advances in the treatment of metastatic colorectal cancer (mCRC) have been made in recent years and mainly consist of the monoclonal antibodies against epidermal growth factor receptor (EGFR) or vascular endothelial growth factor (VEGF) with the combination of chemotherapy." (PMID 32308771, 2020). "Indeed, among treatment options for metastatic colorectal cancer (mCRC), in particular, are two anti-EGFR mAbs, cetuximab and panitumumab, currently indicated for the same subgroup of patients, those with RAS wild-type (wt) metastatic disease." (PMID 31616627, 2019).
metastatic colorectal cancer (continued). "Metastatic colorectal cancer (mCRC) patients treated with anti‐EGFR therapies, including cetuximab and panitumumab, may be subject to these reactions." (PMID 31376243, 2019). "Epidermal growth factor receptor (EGFR) antibodies may have detrimental effects in patients with metastatic colorectal cancer expressing oncogenic Rat sarcoma (RAS)." (PMID 32039027, 2019). "Since these genetic mutations have been emerged as predictive biomarkers for patients who might fail to EGFR-targeted therapy, these preliminary findings indicate that GM may represent a promising therapeutic agent for metastatic colorectal cancer." (PMID 31552177, 2019). "EGFR mAbs alone or in combination with chemotherapies have achieved an increase in unsustainable OS to <10% of metastatic colorectal cancer, and EGFR mAb in combination with radiotherapy has been shown to increase the 5 year OS rate by about 10% to regionally advanced head and neck cancers." (PMID 31508364, 2019). "Importantly, EGFR is also expressed in some epithelial cells and systemic administration of anti-EGFR mAbs will induce adverse effects such as skin rash in a majority of patients with metastatic colorectal cancer." (PMID 30469350, 2018). "Approximately 30% of patients with sCRC have KRAS mutations and are resistant to EGFR inhibitors, and up to 50% of metastatic colorectal cancer (mCRC) cases with KRAS wild-type (WT) do not respond to anti-EGFR therapies." (PMID 30344942, 2018). "Therefore, we conducted this study to assess the relation between EZH2 expression and clinical outcomes in patients with metastatic colorectal cancer treated with anti-EGFR therapeutics." (PMID 28147317, 2017). "The American Society of Clinical Oncology (ASCO) published guidelines in 2009 recommending all patients with metastatic colorectal cancer (mCRC) receive KRAS testing to guide anti-epidermal growth factor receptor (anti-EGFR) monoclonal antibody (MoAb) treatment." (PMID 29202108, 2017). "From our analysis we conclude that as regards KRAS in metastatic colorectal cancer (mCRC) treated with an anti-EGFR antibody a neutral evolution model and not KRAS mutations provides a greater understanding of the clinical outcome." (PMID 28981524, 2017). "In metastatic colorectal cancer (mCRC), treatment with anti-epidermal growth factor receptor (EGFR) monoclonal antibodies cetuximab or panitumumab has demonstrated efficacy in wild-type (WT) RAS mutations and it is now considered imperative this determination at the time of diagnosis." (PMID 28368441, 2017). "Cetuximab, an epidermal growth factor receptor (EGFR)-blocking antibody, was approved for treatment of metastatic colorectal cancer over a decade ago; however, patients' responses to cetuximab vary substantially due to intrinsic and acquired resistance to cetuximab." (PMID 27074568, 2016). "We considered whether the emergence of distinct resistance mechanisms might affect the clinical outcome of metastatic colorectal cancer (CRC) patients treated with anti-EGFR antibodies." (PMID 27929064, 2016). "Several recent studies have reported that patients with metastatic colorectal cancer (CRC) whose primary tumor is located in left side of the colon have more favorable responses to anti-epidermal growth factor receptor (EGFR) antibody therapy than those with right-sided tumors." (PMID 27296289, 2016). "Moreover, both cetuximab and panitumumab are approved for the treatment of patients with EGFR-expressing metastatic colorectal cancer." (PMID 27655662, 2016). "In this study we focused on potential modifications of the EGFR ectodomain that may interfere with antibody binding and activating mutations of RAS, which are known to confer resistance in metastatic colorectal cancer." (PMID 27119512, 2016).